CTLA4 (cytotoxic T-lymphocyte associated protein 4)
Diseases named in the same sentence as CTLA4 in open-access papers (continued):
Sharing a sentence is not in itself a finding about the gene and the disease.
cancer (continued). "Counteracting the immune inhibitory effect of CTLA-4, the FDA-approved CTLA-4-inhibitor ipilimumab shows great anticancer efficacy in a wide range of cancer types." (PMID 31696402, 2019). "Antibodies targeting CTLA-4 and/or PD-1/PD-L1 are one of the most promising therapeutic approaches to treating cancer patients." (PMID 31614774, 2019). "A combination of immune checkpoint inhibitors namely PD-1 and CTLA-4 can effectively kill cancer cells because they function primarily through complementary mechanisms." (PMID 31137625, 2019). "Cancer cells regularly harness CTL antigen 4 (CTLA-4 or CD152) and programmed cell death-1 (PD-1 or CD279) immune-checking molecules to escape detection and elimination by the immune system." (PMID 31694270, 2019). "Antagonizing antibodies against major T-cell inhibitory pathways, such as PD-1/PD-L1 and CTLA-4, have become important parts of cancer therapeutics." (PMID 30863404, 2019). "CTLA-4 targeted antibodies have shown efficacy in the treatment of cancers; it provided therapeutic benefits, but can also lead to severe adverse effects." (PMID 31091813, 2019). "Targeting immune checkpoints such as PD-1, PD-L1, and CTLA-4 have achieved noteworthy benefit in multiple cancers by blocking immunoinhibitory signals and enabling patients to produce an effective antitumor response, especially in patients with CM." (PMID 31169496, 2019). "This new paradigm enables the design or identification of safer and more effective anti-CTLA-4 antibodies for cancer immunotherapy." (PMID 31267017, 2019). "The most famous antibodies used as cancer immunotherapies, which are intensively studied, are anti-CTLA4 and -PD-1 antibodies." (PMID 31013788, 2019). "Blockade of inhibitory immune checkpoints, such as CTLA-4 and PD-1/PD-L1, has changed the classical approach to treat cancer." (PMID 31569553, 2019). "Antibody therapies against the CTLA-4 and PD-1/PD-L1 axes have revolutionized the treatment of cancer." (PMID 30729114, 2019). "Here we report elevated TCR convergence in baseline peripheral blood of those who respond to CTLA-4 blockade for cancer." (PMID 31993050, 2019). "With the development of immunotherapy, more than 20 immunologic molecules, especially drugs against CTLA-4 and PD-1/PD-L1 checkpoint pathways, were designed, shining the gloomy prognosis of malignant tumors." (PMID 30728876, 2019). "In several studies, the expression levels of immune checkpoints CTLA4 or PD-L1 in tumors are reported to have prognostic utility for cancer patients." (PMID 31753019, 2019). "Immunotherapy, especially PD-1/PD-L1 blockage and CTLA-4 blockage, has revolutionized the landscape of cancer treatment in recent years." (PMID 31824865, 2019). "Motivated by the shortcomings of existing non-invasive biomarkers, here we evaluated the use of peripheral blood TCRB repertoire sequencing as a source of predictive biomarkers for response to CTLA-4 monotherapy for cancer." (PMID 31993050, 2019). "T-cell exhaustion, defined as an impaired T-cell capacity to secrete cytokines and proliferate, with overexpression of immune checkpoint receptors (e.g., PD-1, CTLA4, and lymphocyte-activating 3) has been observed in certain types of cancer, including HCC." (PMID 31671581, 2019). "The studies on the role of CTLA-4 and PD-1 expression on T cells in cancer were mainly based on the analyses of circulating T cells." (PMID 31010080, 2019). "Here, we discuss the current immunotherapeutic approaches against cancer, including immune checkpoint blockade with an emphasis on anti-PD-L1 and anti-CTLA-4 monoclonal antibodies." (PMID 31575023, 2019). "Anti-cytotoxic T-lymphocyte-associated antigen 4 (CTLA4), anti-programmed cell death 1 (PD1), and anti-PD1-ligand 1 (PD-L1) monoclonal antibodies have drastically changed the clinical care of cancer." (PMID 31277279, 2019). "The combined use of anti-CTLA-4 and anti-PD-1 blockade in patients with melanoma cancer has now become a first-line treatment after clinical trials." (PMID 31998326, 2019).
cancer (continued). "Data of the HLA- I genotype in advanced cancer patients treated with anti-PD-1 antibody or anti-CTLA-4 antibody was analyzed." (PMID 31623180, 2019). "Following the discovery of CTLA-4 in 1987 and Allison demonstrating its inhibitory effect on T cell functions, he sought to interrupt those inhibitory signals using a blocking antibody against the inhibitory receptor CTLA-4 in a mouse model of cancer." (PMID 30691215, 2019). "Studies on mice deficient of key markers of Tregs, including IL-10, CTLA-4, GITR, or PD-1 that develop severe immune-related disorders indicate that these molecules are crucial for Treg function in a cancer setting." (PMID 31134056, 2019). "Today, the most promising immunotherapies against cancer are based on immune checkpoint blockers (ICB) against CTLA-4 or PD-1/PD-L1." (PMID 31886313, 2019). "This study provided evidence that blockade of CTLA-4 and, therefore, its suppressive activity can enable and potentiate effective immune response against cancer cells in the “brake-off” mechanism." (PMID 31717326, 2019). "Checkpoint inhibitors (CTLA-4, PD-1/PD-L1), adoptive cell transfer, monoclonal antibodies and cancer vaccines are among the most popular cancer immunotherapy modalities available so far." (PMID 30909630, 2019). "Anti-CTLA-4 antibody was the first of several T-cell-targeting antibodies that have been approved for clinical use for cancer immunotherapy." (PMID 31267017, 2019). "Surprisingly, a converging pathway for drug development arising from this study not only reduces toxicity of anti-CTLA-4 antibodies, but also increases their cancer therapeutic effect." (PMID 31267017, 2019). "A total of 826 cancer patients were included: 426 (51.6%) received anti-PD-1/PD-L1 therapy, 264 (32.0%) received anti-CTLA-4 therapy, and 136 (16.5%) received a combination of the two." (PMID 31488205, 2019). "Monoclonal antibodies (mAbs) are a rapidly evolving field in cancer therapy, however a number of newly developed and highly effective mAbs (e.g., anti-CTLA-4 and anti-PD-1) possess pharmacogenomic profiles that remain largely undefined." (PMID 35582142, 2019). "Discovery of the two checkpoint molecules CTLA-4 and PD-1 that function as brakes on the immune system has led to a new approach for treating cancer patients." (PMID 31134056, 2019). "Subsets of NK cells express programmed cell death protein 1 (PD-1) and cytotoxic T lymphocyte-associated antigen 4 (CTLA-4), which have been intensively investigated as immune checkpoint receptors for the development of novel cancer therapeutics." (PMID 30925759, 2019). "Recently, cancer immunotherapies, such as CTLA-4 and PD-1/PD-L1, have sparked intense debate and research because of their substantial clinical benefits for advanced cancer patients." (PMID 31866766, 2019). "Akkermansia plays a key role in improved human fat and sugar metabolism and promotes CD8+ T cell-mediated immune responses to anti-cancer immune modulators like PD-1 and CTLA4 agonists." (PMID 31078141, 2019). "HIV evades the immune response by promoting a state of immune exhaustion, which is similar to the mechanism of how cancers with upregulated PD-L1/PD-1 axis and/or CTLA-4 expression elude immune eradication." (PMID 31113482, 2019). "CTLA-4 was the first checkpoint molecule targeted in cancer treatment, initially in melanoma with dramatic results, and subsequently in other cancer types." (PMID 31877721, 2019). "The strategy of using monoclonal antibodies against two distinct inhibitory receptors on T-cells, PD1, and CTLA-4 is a major breakthrough in the field of cancer immunotherapy." (PMID 30853982, 2019). "To date, immune checkpoint inhibitors (ICIs) have been the most studied class of cancer immunotherapies, including PD-1/PD-L1 blockade and CTLA-4 blockade." (PMID 31779642, 2019). "Our data establish a new paradigm for cancer research that allows for abrogating irAE while increasing CITE of anti-CTLA-4 antibodies." (PMID 31267017, 2019).
cancer (continued). "Recent years have witnessed the wide application of anti-PD-1, anti-CTLA4, and anti-PD-L1 antibodies in various types of cancer." (PMID 31636634, 2019). "The blockade of CTLA-4 by anti-CTLA-4 antibodies results in unrestricted T-cell activation, thus enhancing the T-cell response to the presence of cancer cells." (PMID 31035449, 2019). "Recent major advances in cancer immunotherapy, especially the immune checkpoint inhibitors targeting the PD-1/PD-L1 and CTLA-4 pathways, demonstrate remarkable curative benefits for some cancer patients." (PMID 31024913, 2019). "Recently, the inhibitory effects of CTLA-4 and PD-1 have become major targets in cancer immunotherapies with the development of checkpoint blockade therapeutics such as anti-CTLA-4 and anti-PD-1 antibodies." (PMID 31998326, 2019). "It has been reported that CTLA-4 is overexpressed and correlated with poor prognosis in various types of cancer, including breast cancer, lung cancer, prostate cancer, and cervical cancer." (PMID 31485274, 2019). "Engagement of the ICOS pathway markedly enhances the efficacy of CTLA-4 blockade in cancer immunotherapy in a mouse model of melanoma and prostate cancer." (PMID 32117199, 2019). "Increased mutational load in tumors has been correlated with better responsiveness to CTLA4 or PD-1 blockade, suggesting that T-cell responses against cancer neoantigens are enhanced." (PMID 31275310, 2019). "Immunotherapy, particularly with ICIs, such as PD-1 or PD-L1 inhibitors or CTLA-4 inhibitors, has changed the entire paradigm for the therapeutic landscape of multiple cancer types." (PMID 31607749, 2019). "Immune checkpoint inhibitors, including anti-CTLA-4 and anti-PD-1 mAbs, have recently been shown to be effective in treating some adult cancers." (PMID 31810498, 2019). "In other words, their data showed that, the efficiency of CTLs generated by a cellular vaccine was increased by administrating the cancer patients with anti-CTLA-4 antibody." (PMID 31164886, 2019). "The current study represents by far the largest case series of patients with cancer who experienced ICIPI related to anti-CTLA-4 or anti-PD-1/L1 therapy." (PMID 30728076, 2019). "This will be extremely important, especially in the field of cancer therapy, where major successes have been achieved first using anti-CTLA-4 antibodies and more recently anti-PD-1 antibodies or antibodies to one of its ligands, PD-L1." (PMID 30761152, 2019). "Checkpoint inhibitors mainly targeting PD1/PDL1 and CTLA4 and personalized cancer vaccines have been and still are heavily investigated in clinical trials." (PMID 31798635, 2019). "In the last decade, inhibitors targeting immune checkpoint molecules such as cytotoxic T-lymphocyte antigen 4 (CTLA-4), programmed cell death 1 (PD-1), and programmed cell death-ligand 1 (PD-L1) brought about a major paradigm shift in cancer treatment." (PMID 31192215, 2019). "A study explored CTLA-4 blockade combined with external beam radiotherapy in a cohort of various cancers." (PMID 31905723, 2019). "For example, cytotoxic T lymphocyte-associated antigen 4 (CTLA-4) and the programmed cell death protein 1 pathway (PD-1/PD-L1) checkpoint inhibitors are currently arising as a novel strategy to fight cancer, including GBM." (PMID 30895167, 2019). "The past 8 years have witnessed the revolutionization of cancer treatment by targeting the immune checkpoint receptors CTLA-4 and PD-1 (nivolumab, pembrolizumab, and cemiplimab), as well as PD-L1 (avelumab, durvalumab, and atezolizumab)." (PMID 31186046, 2019). "Taken together, our data reveal a converging pathway for safer and more effective anti-CTLA-4 antibodies in cancer immunotherapy, thus sparing us the dilemma of having to choose between higher efficacy and less toxicity." (PMID 31267017, 2019).
cancer (continued). "The acknowledgement of cancer immunotherapy as breakthrough of the year in 2013 and the award of the Nobel Prize 2018 for the discoveries of anti-CTLA4 and anti-PD-1 as cancer immunotherapy illustrate the paradigm shift in the treatment of cancer patients." (PMID 30764534, 2019). "Cytotoxic T lymphocyte-associated antigen 4 (CTLA4) and programmed cell death protein 1 (PD1) are two immune-checkpoint receptors that have been clinically targeted for cancer immunotherapy." (PMID 31842801, 2019). "To circumvent this issue, here we leveraged the low substitution error rate of the Ion Torrent platform to evaluate convergence as a predictive biomarker for response to anti-CTLA-4 monotherapy in a set of 22 study subjects with cancer." (PMID 31993050, 2019). "Both anti-CTLA-4 monoclonal antibodies and the PD-1 and PD-L1 inhibitors are clinically used for cancer immunotherapy." (PMID 31450710, 2019). "The effect of IL-15 administration combined with checkpoint inhibitors (anti-CTLA-4 and/or anti-PD-1 mAbs) is currently under investigation in patients with cancers refractory to other therapies." (PMID 32010130, 2019). "In fact, studies have shown that there is an interaction between PLR, which reflects the host immune and inflammatory levels, and CTLA-4, which reflects the immune status of cancer." (PMID 31485274, 2019). "Cancer immunotherapy is currently being dominated by immune checkpoint inhibitors and over 1500 clinical trials are registered targeting PD-1, PD-L1 or CTLA-4." (PMID 31324216, 2019). "Blocking CTLA-4 removes the inhibitory signal received by T-cells during their antigen-specific stimulation and allows them to activate and target cancer cells for destruction." (PMID 31366129, 2019). "Antibodies targeting CTLA-4 (Ipilimumab) and PD-1 (Nivolumab, Pembrolizumab) have shown a great promise for the treatment of different cancers." (PMID 31824260, 2019). "In the future, the accumulation of such structural studies with other anti-CTLA-4 antibodies can enhance the understanding of the mechanism related to the therapeutic efficacy of anti-CTLA-4 antibodies in cancer immunotherapy." (PMID 30917623, 2019). "Antibodies targeting immune checkpoints including CTLA-4, PD-1, and PD-L1 have now been approved and used in the clinics for diverse cancer treatments." (PMID 32117199, 2019). "More recently, promising results were also shown by administration of CTLA-4 inhibitor in cancer treatment." (PMID 31485274, 2019). "By contrast, certain cancer immunotherapy, such as CTLA4 blockade, can induce T-cell activation and proliferation, and increase the number of TCR clonotypes and diversity." (PMID 30886908, 2019). "While CTLA-4 is constitutively expressed on Treg both in and outside cancer tissues, cell surface CTLA-4 is minimally detectable among circulating Treg and those in lymphoid organs." (PMID 31681327, 2019). "Our work provides a new paradigm in the field on how to target CTLA-4 effectively for cancer immunotherapy." (PMID 31267017, 2019). "For instance, researchers have shown that targeting CTLA4 with antibodies through immunotherapy approaches can help treat advanced cancer." (PMID 31906017, 2019). "A clinical trial (NCT03347123) is testing the combination of anti-CTLA-4, anti-PD-1 and epacadostat in advanced cancer." (PMID 31112568, 2019). "Approaches to further enhance the efficacy of iPSC-based cancer vaccines include concurrent treatment with PD-1/CTLA-4 checkpoint inhibitors, chemotherapy, or radiation therapy." (PMID 31338094, 2019). "It has revolutionized some advanced cancer’s treatment and outcome, particularly with the development of checkpoint inhibitors targeting cytotoxic T lymphocytes antigen 4 (CTLA-4) and programmed cell death 1 (PD-1)." (PMID 31262050, 2019). "The use of monoclonal antibodies (mAbs) targeting CTLA-4 or PD-1 checkpoint pathways have been approved for clinical use leading to durable clinical responses in various cancer types." (PMID 31234588, 2019).
cancer (continued). "Here we describe a new paradigm for developing safer and more effective anti-CTLA-4 antibodies with broad implications for cancer immunotherapy." (PMID 31267017, 2019). "Since M2-type TAMs along with cancer cells possess CTLA-4, PD1 and PDL1 ligands, targeting TAMs stand as a promising immunotherapeutic approach to treat cancer." (PMID 30925924, 2019). "Harnessing immune responses against cancer by ICB was first realized using anti-CTLA-4 Abs, and has opened a new era for cancer immunotherapy." (PMID 30841554, 2019). "In this context, elucidating the mechanisms of CTLA-4 and PD-1 T-cell inhibitory signalling has led to development of promising cancer immunotherapy tools, including blocking monoclonal antibodies (mAb) targeting these so-called ‘immune checkpoints'4,5." (PMID 31350404, 2019). "In our comparison of four cancers, CTLA-4-TIGIT-PD-1-TIM-3-BTLA- LAG-3 were among those most increased in expression and having the greatest association with OS." (PMID 30922393, 2019). "Targeting PD-L1 or CTLA-4 has led to durable responses in different cancer entities, but only in a subset of patients." (PMID 30413826, 2019). "Programmed cell death 1/programmed death ligand 1 (PD-1/PD-L1) and CTLA-4 are the most common targets of immune-blocking cancer treatments, and many clinical trials are currently investigating the use of corresponding monoclonal antibodies." (PMID 31195368, 2019). "The proportion of cells with PD-1 and with CTLA-4 expression was the highest in the BALF harvested from the cancer site." (PMID 31010080, 2019). "Recent studies have reported that CTLA-4 is upregulated in chronic infections and malignant neoplasms, contributing to host immune dysfunction." (PMID 31665022, 2019). "A combination of IL12 and ADCC-inducing anti-PD-L1 or anti-CTLA4 showed impressive results in pre-clinical murine cancer models, including in a glioma model." (PMID 31614774, 2019). "Only partial patients respond to the pathways of immune checkpoint treatment, namely, CTLA-4 and PD-1/PD-L1, probably caused by profound immunosuppression, which may be partly induced by myeloid-derived suppressor cells (MDSCs), a potential predictive marker for the cancer therapy response." (PMID 31462894, 2019). "In conclusion, combination of CTLA-4 and PD-1 blockers was effective in increasing the response and survival rates in multiple cancer types, but it also increased the incidence of adverse events." (PMID 31196207, 2019). "CTLA-4 plays an essential role in the adjustment of the host immune system, but its expression is upregulated in several chronic infections and cancers." (PMID 31665022, 2019). "It is essential to mention that targeting CTLA-4 and the PD-L1/PD-1 axis simultaneously in cancer patients has produced synergistic effects in numerous cases." (PMID 31717326, 2019). "Ipilimumab was the first CTLA-4 inhibitor to be tested and approved for the treatment of cancer patients." (PMID 31581738, 2019). "Immune checkpoint inhibitors that block CTLA-4 (cytotoxic T-lymphocyte-associated protein 4), PD1 (programmed death 1), or PD-L1 (programmed death-ligand 1) have demonstrated significant promise in the clinic across a range of cancer indications." (PMID 31221204, 2019). "Discovery and clinical application of immune checkpoint inhibitors (ICIs) i.e., monoclonal antibodies (mAbs) blocking specific immune checkpoints CTLA-4 and PD-1/PD-L1, have revolutionized therapy of various cancers." (PMID 31468283, 2019). "Immune checkpoint inhibitors (ICIs) against PD-1, PD-L1, and CTLA-4 have led to the revolution of cancer immunotherapy." (PMID 31807308, 2019). "This outcome would not be possible by current approach that aims at breaking a physiological CTLA-4 checkpoint of immune tolerance to achieve better cancer immunity." (PMID 31267017, 2019).